LYNX1 (Ly6/neurotoxin 1)
Description:
Acts in different tissues through interaction to nicotinic acetylcholine receptors (nAChRs). The proposed role as modulator of nAChR activity seems to be dependent on the nAChR subtype and stoichiometry, and to involve an effect on nAChR trafficking and its cell surface expression, and on single channel properties of the nAChR inserted in the plasma membrane. Modulates functional properties of nicotinic acetylcholine receptors (nAChRs) to prevent excessive excitation, and hence neurodegeneration. Enhances desensitization by increasing both the rate and extent of desensitization of alpha-4:beta-2-containing nAChRs and slowing recovery from desensitization. Promotes large amplitude ACh-evoked currents through alpha-4:beta-2 nAChRs. Is involved in regulation of the nAChR pentameric assembly in the endoplasmic reticulum. Shifts stoichiometry from high sensitivity alpha-4(2):beta-2(3) to low sensitivity alpha-4(3):beta-2(2) nAChR (By similarity). In vitro modulates alpha-3:beta-4-containing nAChRs. Reduces cell surface expression of (alpha-3:beta-4)(2):beta-4 and (alpha-3:beta-4)(2):alpha-5 nAChRs suggesting an interaction with nAChR alpha-3(-):(+)beta-4 subunit interfaces and an allosteric mode. Corresponding single channel effects characterized by decreased unitary conductance, altered burst proportions and enhanced desensitization/inactivation seem to depend on nAChR alpha:alpha subunit interfaces and are greater in (alpha-3:beta-2)(2):alpha-3 when compared to (alpha-3:beta-2)(2):alpha-5 nAChRs. Prevents plasticity in the primary visual cortex late in life (By similarity).
Synonyms: SLURP2
Tractability: Antibody: UniProt places it where antibodies can reach, with medium confidence; UniProt predicts a signal peptide or a membrane-spanning region; its Gene Ontology location is reachable by antibodies, with medium confidence.
Gene: Protein-coding gene on chromosome 8 (142,771,197 to 142,777,859, reverse strand). Ensembl gene ENSG00000180155.
Subcellular location: Cell membrane; Cell projection, dendrite; Endoplasmic reticulum
Gene Ontology:
Molecular function: acetylcholine receptor binding; acetylcholine receptor regulator activity; acetylcholine receptor inhibitor activity
Biological process: regulation of neurotransmitter receptor activity; acetylcholine receptor signaling pathway
Cellular component: endoplasmic reticulum; plasma membrane; dendrite; synapse
Genetic constraint (gnomAD): Loss-of-function variants: 8 observed, 9.01 expected, observed/expected ratio (o/e) 0.89, 90% interval 0.52 to 1.58. That is too few expected variants to judge how well the gene tolerates losing a copy. Missense variants: 158 observed, 159.08 expected, observed/expected ratio (o/e) 0.99, 90% interval 0.87 to 1.13. Synonymous variants: 73 observed, 66.17 expected, observed/expected ratio (o/e) 1.1, 90% interval 0.91 to 1.34.
Homologues: Orthologues: chimpanzee LYNX1 (99% identical), pig LYNX1 (86% identical), guinea pig LYNX1 (82% identical), Caenorhabditis elegans D1081.20 (25% identical), rat Slurp2 (20% identical), mouse Slurp2 (19% identical). Paralogues in human: LY6D (34% identical).
Diseases named in the same sentence as LYNX1 in open-access papers:
LYNX1 is named in the same sentence as 38 diseases in open-access papers, as found by Europe PMC text mining. Sharing a sentence is not in itself a finding about the gene and the disease. The quoted sentences say what the papers report.
lung carcinoma (6 papers, 2019 to 2021). "Knock-down of LYNX1 enhanced the growth of A549 cells; overexpression of LYNX1 conversely resulted in cell cycle arrest in lung cancer." (PMID 33330109, 2020). "Another modulator of nAChRs, Lynx1, was demonstrated to induce cell cycle arrest and apoptosis in lung carcinoma cells, pointing on its possible usage for glioma treatment too." (PMID 32650495, 2020). "Knockdown of LYNX1 increases growth of lung cancer cells by siRNAs, while enriched expression of LYNX1 in lung cancer cells decreases cell proliferation." (PMID 33299855, 2020). "Silencing of the LYNX1 gene in lung carcinoma A549 cells leads to the significant increase in the cancer cell growth." (PMID 31150435, 2019). "Besides SLURP-1, lung cancer cells express Lynx1,–another Ly6/uPAR protein, also involved in control of their growth." (PMID 34595181, 2021). "Based on these previous reports, LYNX1 is a tumor suppressor in lung cancer, but it has been unclear whether LYNX1 is a tumor suppressor or an oncogenic in other cancers." (PMID 33299855, 2020). "The decreased Lynx1 level was revealed in lung cancer cells in comparison with normal cells." (PMID 31150435, 2019). "Human Lynx1 was also found to participate in the regulation of the lung cancer cells growth." (PMID 31150435, 2019). "However, it is unclear whether and by what mechanism LYNX1 has a potential function in lung cancer progression and tumor immunology." (PMID 33299855, 2020). "Additionally, Lynx1 may have beneficial effects in preventing lung cancer endogenously since the increased expression of Lynx1 in A549 lung cancer cells decreased the proliferation, and the inverse knockdown of Lynx1 in these cells led to an increased proliferation." (PMID 34684676, 2021).
glioma (4 papers, 2020 to 2021). A benign or malignant brain and spinal cord tumor that arises from glial cells (astrocytes, oligodendrocytes, ependymal cells). "Importantly, previous studies reported that AIFM3, LDHD, LYNX1, SCN2B or TMEM56 were all negatively corelated with glioma, and GINS1, KIFC1, NUF2, NUSAP1 or TPX2 were both positively related to glioma progression." (PMID 33277782, 2021).
schizophrenia (3 papers, 2014 to 2021). A major psychotic disorder characterized by abnormalities in the perception or expression of reality. "Of note, a mouse model of 22q11 microledetion syndrome, a genetic lesion associated with increased risk of ADHD, autism spectrum disorders, schizophrenia, and other psychiatric conditions, showed significantly reduced Lynx1 expression in prefrontal cortex." (PMID 25359633, 2014). "In addition, we confirmed Cap2, Chgb, Cpne6, Lynx1, and Mbp; which were selected among gene products implicated in schizophrenia and neurological disorders by the DAVID algorithm (p < 2.35E-03)." (PMID 28344592, 2017).
breast carcinoma (2 papers, 2019 to 2020). "Previous studies have shown that LYNX1 mRNA and protein are expressed in lung, colon, epidermis, and breast cancer cells." (PMID 33299855, 2020). "The mRNA and protein expression of the LYNX1 has been found in lung, colon, epidermis, and breast cancer cells, and in lung adenocarcinoma A549 and colon carcinoma HT-29 cell lines, the colocalization of LYNX1 with α7-nAChRs has been reported in cell membranes." (PMID 33299855, 2020). "The Lynx1 expression both at the mRNA and protein level was detected in normal oral keratinocytes, and lung, colon, epidermal, and breast cancer cells, but not in embryonic kidney cells." (PMID 31150435, 2019).
colon carcinoma (2 papers, 2019 to 2020). "Colocalization of Lynx1 with α7-nAChRs in lung and colon cancer cells was observed." (PMID 31150435, 2019). "Here, we studied the Lynx1 expression in human cells of epithelial origin (normal oral keratinocytes Het-1A, embryonic kidney cells HEK-293T, epidermoid carcinoma A431, breast adenocarcinoma MCF-7, lung adenocarcinoma A549 and colon carcinoma HT-29)." (PMID 31150435, 2019). "Co-localization of Lynx1 with α7-nAChRs was revealed in a cell membrane for lung adenocarcinoma A549 and colon carcinoma HT-29 cells, but not for breast adenocarcinoma MCF-7 and epidermoid carcinoma A431 cells." (PMID 31150435, 2019).
lung adenocarcinoma (2 papers, 2019 to 2020). A carcinoma that arises from the lung and is characterized by the presence of malignant glandular epithelial cells. "In lung adenocarcinoma A549 cells, endogenous LYNX1 expression controls the nicotine-induced upregulation of α7-nAChRs that occurs during cell growth." (PMID 33299855, 2020). "Endogenous Lynx1 controls the nicotine-induced up-regulation of the expression of α7 type nAChRs in lung adenocarcinoma A549 cells as well as the cell growth." (PMID 31150435, 2019).
ovarian serous cystadenocarcinoma (2 papers, 2020 to 2023). A malignant serous cystic epithelial neoplasm arising from the ovary. "High LYNX1 expression in ovarian serous cystadenocarcinoma (OVs) was associated with tumor residual disease (RD)." (PMID 33299855, 2020). "Ly6/neurotoxin 1 (LYNX1) has been suggested as a prognostic factor in ovarian serous cystadenocarcinoma and glioblastoma." (PMID 37705968, 2023). "In the current study, we used The Cancer Genome Atlas (TCGA), gene set enrichment analysis (GSEA), and Kaplan–Meier plotter to comprehensively analyze the expression of LYNX1 and its relationship with the prognosis of patients with ovarian serous cystadenocarcinoma (OVs)." (PMID 33299855, 2020).
amyotrophic lateral sclerosis (1 paper, 2022). Amyotrophic lateral sclerosis (ALS) is a neurodegenerative disease characterized by progressive muscular paralysis reflecting degeneration of motor neurons in the primary motor cortex, corticospinal tracts, brainstem and spinal cord. "A better understanding of these unanswered questions about Lynx1 could shed light on opportunities to preserve the structure and function of NMJs and muscles during aging and other chronic conditions, including amyotrophic lateral sclerosis (ALS)." (PMID 35372356, 2022).
asthma (1 paper, 2021). "Due to the negative regulation of Lynx1 on nAChR activity, especially through the inhibition of GABAergic-mediated mucin upregulation, Lynx1-mimetics have been suggested as potential treatment options in asthma and COPD." (PMID 34684676, 2021).
astrocytoma (1 paper, 2017). "No fusions involving LYNX1 have been reported in the literature so far, but the suggested fusion partner FCF1 was involved in a TIMM9-FCF1 fusion in an astrocytoma." (PMID 28893231, 2017).
cognitive deficits (1 paper, 2026). "Moreover, treatment with a water-soluble LYNX1 analogue was shown to prevent amyloid beta-induced blockade of memory-related synaptic plasticity, indicating LYNX1 may be a potential therapeutic target for improving cognitive deficits in neurodegenerative diseases." (PMID 41542061, 2026).
Crohn disease (1 paper, 2021). A gastrointestinal disorder characterized by chronic inflammation involving all layers of the intestinal wall, noncaseating granulomas affecting the intestinal wall and regional lymph nodes, and transmural fibrosis. "Using expression quantitative trait loci (eQTL) combined with genome-wide association study (GWAS) patterns in humans, Lynx1 was associated with Crohn’s disease." (PMID 34360971, 2021).
epilepsy (1 paper, 2022). A brain disorder characterized by episodes of abnormally increased neuronal discharge resulting in transient episodes of sensory or motor neurological dysfunction, or psychic dysfunction. "LYNX1-mediated mechanisms could be potentially linked to the increased risk of epilepsy based on a patient-specific gene expression profile enriched with known genes associated with epilepsy in NPCs derived from one FXS donor with epilepsy." (PMID 36506088, 2022). "We found reduced LYNX1 expression that via tPA-dependent mechanism could affect process growth in FXS NPCs and may in combination with patient-specific transcriptional regulation of genes related to epilepsy contribute to the FXS epilepsy phenotype." (PMID 36506088, 2022).
gastric cancer (1 paper, 2025). A primary or metastatic malignant neoplasm involving the stomach. "Two genes (PSCA and LYNX1) presented causal associations with gastric cancer." (PMID 41209561, 2025).
mastitis (1 paper, 2024). Inflammation of breast tissue during lactation or postpartum due to an obstructed duct or infection. "Among them, cnvr_137 contains genes such as LY6D, LYNX1, LYPD2, SLURP1,THEM6, PSCA, TSNARE1, and ARC associated to clinical mastitis in US Holstein dairy cows." (PMID 38771855, 2024).
memory impairment (1 paper, 2018). "In addition, ws-Lynx1 is capable of correctingAβ1-42–induced impairments of hippocampal synapticplasticity, which underlies memory impairment and other cognitive dysfunctionsin AD." (PMID 30397527, 2018).
non-small cell lung carcinoma (1 paper, 2020). A group of at least three distinct histological types of lung cancer, including non-small cell squamous cell carcinoma, adenocarcinoma, and large cell carcinoma. "A prognostic risk index, grounded on four persister genes (LYNX1, SYNPO, GADD45B, and PDLIM1), was constructed in non-small-cell lung cancer patients from The Cancer Genome Atlas Program (TCGA) using stepwise Cox regression analysis." (PMID 33330109, 2020).
oropharyngeal tumors (1 paper, 2023). "A quantitative sequencing study found that LYNX1 expression significantly increased the recurrence of methylation groups in oropharyngeal tumors." (PMID 37705968, 2023).
ovarian carcinoma (1 paper, 2020). A malignant neoplasm originating from the surface ovarian epithelium. "We retrieved LYNX1 gene expression data and clinical information of 376 patients with ovarian cancer from The Cancer Genome Atlas (TCGA) project website." (PMID 33299855, 2020). "The expression of the gene in the ovarian cancer samples was divided into high-expression and low-expression LYNX1 with the median as the cut-off point." (PMID 33299855, 2020). "Therefore, our findings reveal the potential regulating role of LYNX1 in inflammation with ovarian cancer." (PMID 33299855, 2020). "Few studies have reported the function of LYNX1 in ovarian cancer." (PMID 33299855, 2020). "LYNX1 may modulate α7-nAChR signaling in cancer cells because LYNX1 is colocalized with α7-nAChRs in epithelial cells, and 90% of ovarian cancers are epithelial ovarian cancer." (PMID 33299855, 2020). "Thus, LYNX1 may regulate the expression of α7- nAChR through different signaling pathways and change the levels of Ach and nicotinic receptors to regulate the growth of ovarian cancer cells." (PMID 33299855, 2020). "Until now, there have been no studies into the role of LYNX1 in ovarian cancer." (PMID 33299855, 2020). "Although the mechanism of nAChR signaling has not been reported for ovarian cancer, we speculate that LYNX1-related promotion of ovarian cancer cell growth may occur via modulation of α7-nAChR and activation of different intracellular signaling cascades." (PMID 33299855, 2020).
cancer (4 papers, 2019 to 2025). A tumor composed of atypical neoplastic, often pleomorphic cells that invade other tissues. "After multivariate analysis, which produced an HR of 1.566 (95% CI, 1.13–2.17; p = 0.007), along with primary therapy outcome, cancer status, and age, LYNX1 were still independently associated with DSS." (PMID 33299855, 2020). "After multivariate analysis, which produced an HR of 1.698 (95% CI, 1.22–2.363; p = 0.002), along with primary therapy outcome, cancer status, and age, LYNX1 still independently associated with OS." (PMID 33299855, 2020). "Data obtained revealed the ability of ws-Lynx1 to regulate homeostasis of cancer cells via interaction with α7-nAChRs, causing the cell cycle arrest and activation of proapoptotic intracellular cascades." (PMID 31150435, 2019). "Gene set enrichment analysis (GSEA) was performed, and the correlation between LYNX1 expression and cancer immune infiltrates was investigated via single sample gene set enrichment analysis (ssGSEA)." (PMID 33299855, 2020). "Thus, snake α-cobratoxin from Naja kaouthia, human-secreted epithelial protein SLURP-1, as well as human protein Lynx1 found in the nervous system, skin, and lungs were demonstrated to be effective anti-cancer agents." (PMID 41590700, 2025). "Additionally, when LYNX1 was highly expressed in OVs, we found that higher levels of LYNX1 expression were correlated with poorer primary therapy and poorer cancer status for poorer OS and DSS." (PMID 33299855, 2020). "In many cancer types, an increase in the somatic cell copy number of 8q is associated with the most common increase in copy number, but LYNX1 has not been extensively studied." (PMID 33299855, 2020). "Increased LYNX1 expression was enriched in clinical stages III/IV (p = 0.787), primary therapy outcomes PR-CR (p = 0.320), cancer status with tumor (p = 0.319), histological grade G3/G4 (p = 0.967), tumor residual disease (RD) (p = 0.010), and anatomic neoplasm subdivision bilateral (p = 0.912)." (PMID 33299855, 2020). "The persister gene panel (LYNX1, SYNPO, GADD45B, and PDLIM1) was established and its role to elucidate radio-response and clinical outcome after radiotherapy was subsequently validated across several cancer types." (PMID 33330109, 2020).
tumor (2 papers, 2020 to 2025). "Increased LYNX1 expression in OVs significantly associated with tumor RD (odds ratio, OR = 2.08 for NRD vs. RD) (p = 0.01) and age (OR = 0.55 for <60 vs. ≥60) (p = 0.004)." (PMID 33299855, 2020). "In addition, we used the single sample gene set enrichment analysis (ssGSEA) to investigate the correlation between LYNX1 and tumor-infiltrating immune cells." (PMID 33299855, 2020).
neurodegenerative disease (1 paper, 2018). A disorder of the central nervous system characterized by gradual and progressive loss of neural tissue and neurologic function. "Our findings suggest that thewater-soluble Lynx1 analogue may be a promising agent for the improvement ofcognitive deficits in neurodegenerative diseases." (PMID 30397527, 2018).
LYNX1 also shares sentences with these, for which no sentence is quoted: psychiatric disorder (2 papers); Alzheimer disease (1); amblyopia (1); Anxiety (1); autism spectrum disorder (1); bladder cancer (1); breast adenocarcinoma (1); epidermoid carcinoma (1); fragile X syndrome (1); glioblastoma (1); hypertriglyceridemia (1); Infertility (1); neurological disorders (1); nicotine addiction (1); oropharyngeal cancers (1); Palmoplantar keratoderma (1).